GLI1 (GLI family zinc finger 1)
Diseases named in the same sentence as GLI1 in open-access papers (continued):
Sharing a sentence is not in itself a finding about the gene and the disease.
bacteremia (1 paper, 2018). "E. coli bacteremia caused a marked increase in both the number of Gli1+LKS cells and the level of Gli1 protein expression by LKS cells." (PMID 29535725, 2018). "By 48 h of bacteremia, the percentage of Gli1+ cells was significantly increased in LKS, LKS−, lin−c-kit+, lin−, and lin+ cell subpopulations." (PMID 29535725, 2018). "Along with the increased expression of SHH in the bone marrow, expression of Gli1 by marrow cells was significantly upregulated at both mRNA and protein levels following bacteremia." (PMID 29535725, 2018). "The interesting observation was that the increase in BrdU incorporation into LKS cells following bacteremia was essentially in those cells expressing Gli1." (PMID 29535725, 2018). "The percentage of BrdU+Gli1+ cells in LKS cell subpopulation was significantly increased 24 h following bacteremia." (PMID 29535725, 2018). "The results showed that the increase in proliferative activity (as reflected by cell BrdU incorporation) in LKS cells following bacteremia was essentially in those cells expressing Gli1." (PMID 29535725, 2018). "Twenty-four hours following bacteremia, the percentage of Gli1+ cells was significantly increased in LKS, lin−c-kit+ and lin+ cell subpopulations." (PMID 29535725, 2018). "It is apparent that the phenotypic conversion of Gli1+ LKS− cells may also contribute to the marked increase in the number of Gli1+ LKS cells in BMCs following bacteremia in our current study." (PMID 29535725, 2018). "Mice with Gli1 gene deletion showed attenuation in activation of marrow hematopoietic stem/progenitor cell proliferation and inhibition of increase in blood granulocytes following bacteremia." (PMID 29535725, 2018). "Although the percentage of Gli1+ cells in the LKS− subpopulation and the level of Gli1 protein expression by LKS− cells increased, the total number of Gli1+ LKS− cells in BMCs significantly reduced by 48 h following bacteremia." (PMID 29535725, 2018). "MCF of Gli1 was significantly elevated in LKS, LKS−, lin−c-kit+, lin−, and lin+ cell subpopulations 48 h following bacteremia." (PMID 29535725, 2018).
basaloid squamous cell carcinoma of the skin (1 paper, 2019). "In particular, GLI1 may be useful to differentiate BCCs from basaloid squamous cell carcinoma of the skin, another basaloid tumor that is rare but diagnostically challenging." (PMID 31756206, 2019).
benign leiomyoma (1 paper, 2022). "In our previous studies, we demonstrated that GLI1 exhibited a higher expression in LMS compared to the myometrium and benign leiomyoma." (PMID 34642915, 2022).
brachydactyly type A1 (1 paper, 2024). A rare, congenital limb malformation characterized by shortened or underdeveloped middle phalanges of all digits, that are sometimes fused with the terminal phalanges. "The mutation in the Ihh variant alters Gli1–DNA binding patterns and weakens cellular proliferation and migration processes, thereby deepening our understanding of the pathogenesis of Brachydactyly type A1 (BDA1) and the involvement of Ihh signaling in cartilage development." (PMID 38540766, 2024).
cardiac hypertrophy (1 paper, 2017). "Removal of Gli1 + cells reduces the pressure overload-induced cardiac hypertrophy and cardiac fibrosis." (PMID 28790436, 2017). "In addition, we found expression of Gli1 was upregulated only at the late stage of cardiac hypertrophy (day 28)." (PMID 28790436, 2017).
Carpenter syndrome (1 paper, 2025). An extremely rare autosomal recessive syndrome characterized by premature closure of cranial sutures leading to cone-shaped head, fusion of the digits, and the presence of more digits than normal. "In RAB23-deficient mice, which mimic Carpenter syndrome in humans, the lack of functional RAB23 results in overt FGF10, Hh and Nodal signaling with consequent misexpression of downstream signal transducers (pERK1/2, Gli1, Lefty1/2 and Pitx2)." (PMID 40261407, 2025).
cartilage tumor (1 paper, 2019). "Our identification of potential target genes that are unique and common to GLI1 and GLI2 in neoplastic chondrocytes contributes to elucidating potential pathways through which Hh signaling impacts cartilage tumor biology." (PMID 30695055, 2019).
choriocarcinoma (1 paper, 2014). An aggressive malignant tumor arising from trophoblastic cells. "Downregulation of Gli1, Gli2, Gli3 and Kif7 was demonstrated in clinical samples of choriocarcinoma and hydatidiform moles as well as choriocarcinoma cell lines when compared with normal placentas." (PMID 25265279, 2014).
chronic pancreatitis (1 paper, 2012). A chronic inflammatory process causing damage and fibrosis of the pancreatic parenchyma. "More than 5 folds decrease of Shh and 2 fold decrease of GLI1 mRNA expression was found in the pancreatic tissues of sulindac treated chronic pancreatitis mice (p < 0.05)." (PMID 22920325, 2012). "Our results imply that the aberrant Shh/GLI1 pathway could be involved in pancreatic desmoplasia in caerulein induced chronic pancreatitis." (PMID 22920325, 2012).
classical Hodgkin lymphoma (1 paper, 2025). "A previous study had suggested that HES7 transcriptional inhibition of Gli1 expression and Hedgehog signaling may cause drug resistance to PD-1 therapy in classical Hodgkin lymphoma." (PMID 40404896, 2025).
coloboma (1 paper, 2018). An abnormality in which a part of a structure in one or both eyes is missing. "We find that, indeed, loss of one or both copies of gli1 partially rescues the coloboma phenotype in ptch2tc294z mutants." (PMID 30333214, 2018). "Gli1 is the major transcriptional activator downstream of Hh signaling in zebrafish, and we reasoned that if Gli1 activity is necessary for coloboma, loss of gli1 would rescue this phenotype." (PMID 30333214, 2018).
Coma (1 paper, 2021). The complete absence of wakefulness and consciousness, which is evident through a lack of response to any form of external stimuli. "Interestingly, we observed a significant increase in the general activity in COMA patient–derived fibroblasts compared with control cells resulting in higher basal expression levels of GLI1, GLI2, GLI3, and PTCH1." (PMID 33024317, 2021).
Cystic kidneys (1 paper, 2018). "Cystic kidneys of several mouse models have shown upregulation of Gli1, a transcriptional target of the Hh pathway, and Hh inhibition reduced cAMP-mediated cysts of cultured embryonic kidneys of several PKD mouse models." (PMID 29563577, 2018).
dementia (1 paper, 2025). Loss of intellectual abilities interfering with an individual's social and occupational functions. "Other genes previously associated with AD or dementia were differentially expressed in both brain regions: CHI3L2, FCGBP, GLI1, STAB1, APOC1, MYO7A, and long non‐coding RNA JHDM1D‐AS1." (PMID 39876821, 2025).
depression (1 paper, 2019). "Our investigations showed that chronic unpredictable mild stress induced depression results declined expression of BDNF, Wnt/β-catenin, Shh and its downstream transcription factors GLI1/2/3 and NKX2.2 in the hippocampus of male Wistar rat." (PMID 31193084, 2019).
diabetic retinopathy (1 paper, 2022). "This was particularly interesting because we previously found that Gli1 expression was significantly higher in patients with diabetic retinopathy and significantly lower in patients with RRD." (PMID 36044534, 2022).
diarrheal disease (1 paper, 2022). The condition of having at least three loose or liquid bowel movements each day. "Our study reports five such proteins, RAPH1, GCNT7, ADAMTS1, GLI1, and SEC31B, which are strong binding partners of other significant proteins and could thus be targeted for the discovery of a common medication system against diarrheal disease." (PMID 36473896, 2022).
dry mouth (1 paper, 2022). "Our results indicated that TRPV1 promotes neural regeneration at the taste buds via Shh/Gli1 signaling, thus serving as a useful target for the clinical treatment of dry mouth." (PMID 36676024, 2022). "In this study, we investigated NF distribution, Shh/Gli1 expression, and the role of TRPV1 in dry mouth by using a mouse model of dry mouth syndrome." (PMID 36676024, 2022).
ductal breast carcinoma (1 paper, 2016). "Staining for GLI1, Shh and NF-κB was analyzed by employing a tissue microarray composed of 51 ductal breast carcinoma specimens (G1: n = 10; G2: n = 31; and G3: n = 10)." (PMID 26843616, 2016). "We found a positive correlation between nuclear GLI1 expression and tumor grade in ductal carcinoma cases." (PMID 26843616, 2016). "In this study, we assessed the expression levels of GLI1, Shh and NF-κB in 51 ductal breast carcinoma specimens by immunohistochemical analysis and their correlations with clinico-pathological variables." (PMID 26843616, 2016). "Accordingly, we assessed the expression of Hh pathway members (GLI1, Shh and NF-κB) in 51 ductal breast carcinoma specimens by immunohistochemical analysis, and we correlated their expression with clinico-pathological variables." (PMID 26843616, 2016).
epithelioid mesothelioma (1 paper, 2022). "Finally, using the TCGA database, we investigate if GLI1 is differentially expressed in epithelioid mesothelioma compared to biphasic MPM." (PMID 36358635, 2022).
head and neck cancer (1 paper, 2016). A primary or metastatic malignant neoplasm affecting the head and neck. "In conclusion, the present study is the first to identify Gli-1 and Gli-2 as prognostic factors in patients with HPV negative head and neck cancer undergoing surgery and adjuvant radiotherapy." (PMID 27918595, 2016).
Hepatic steatosis (1 paper, 2016). Steatosis is a term used to denote lipid accumulation within hepatocytes. "In case of down-regulated Gli1 and Gli3, prominent lipogenic transcription factors (e.g. Ppara/g, Srebf1) are up-regulated and influence an entire network of several genes associated with lipid metabolism which finally ends up with hepatic steatosis." (PMID 27185526, 2016).
Hyperglycemia (1 paper, 2020). An increased concentration of glucose in the blood. "MET exerted protective effect against hyperglycemia-induced endothelial impairment, which was contributed to MET improving HG-inhibited GLI1 activity and BNIP3 expression in HUVECs." (PMID 33162888, 2020).
hyperplastic (1 paper, 2021). "In the hyperplastic prostate, the mRNA level of SMO and GLI1–3 was significantly increased over 2-fold and the protein level of these molecules was consistently increased." (PMID 34006832, 2021).
Hyperthermia (1 paper, 2025). "Hyperthermia promotes GLI1 binds to HSPs, increase GLI1 ubiquitination level and degrade GLI1 through proteasome pathway." (PMID 41497797, 2025).
Hypoglycemia (1 paper, 2024). A decreased concentration of glucose in the blood. "On the other hand, various studies have proven that SGLT2 inhibitors and GLI-1 RA in type 2 DM patients can reduce the risk of hypoglycemia." (PMID 38243951, 2024).
infiltrating urothelial bladder carcinoma (1 paper, 2020). "GLI1 showed a significant level of co-expression in mucinous breast carcinoma and ovarian serous surface papillary carcinoma, whereas AMHR2, CHRD, and ACVR2A showed a similar pattern in ovarian serous papillary carcinoma, superficial bladder carcinoma and infiltrating urothelial bladder carcinoma." (PMID 31973134, 2020).
injury (1 paper, 2021). Damage inflicted on the body as the direct or indirect result of an external force, with or without disruption of structural continuity. "Further evidence was provided by in vivo study, which showed that disruption of Gli1 reversed myeloid Foxo1 deficiency-mediated cytoprotection, evidenced by augmented IR-induced liver injury and enhanced NEK7/NLRP3 activity." (PMID 33288903, 2021).
intestinal cancer (1 paper, 2025). "Our findings demonstrated a significant decline in GLI1 expression in matched normal tissue compared to intestinal cancer tissue." (PMID 39744485, 2025). "Furthermore, linear correlation analysis showed a positive correlation between the mRNA expression of NLRP3 and GLI1 in bowel cancer tissue." (PMID 39744485, 2025).
jaw cysts (1 paper, 2013). "Gli1 is another well-defined hedgehog signaling effector, but there is no report on occurrence of jaw cysts in Gli1 transgenic mice, suggesting that GLI2 is more essential than GLI1 in KCOT development." (PMID 23951062, 2013).
joint disease (1 paper, 2023). "To determine the relationship between GLI1 expression and the RA process, we collected synovial tissue from RA patients and noninflammatory joint disease donors and obtained informed consent from the patients." (PMID 37929702, 2023).
kidney cancer (1 paper, 2020). Primary or metastatic malignant neoplasm involving the kidney. "Both SHH and GLI1 have been reported to be overexpressed in gastric, bile duct, lung, and kidney cancers, among others." (PMID 33291316, 2020).
kidney papillary carcinoma (1 paper, 2020). "Noticeably, in bladder, colorectal and kidney papillary carcinoma, GLI2 (and GLI1) expression shared bad prognostic value with that of TGFB genes, while high HH expression was associated with a positive outcome." (PMID 32879407, 2020).
large cell carcinoma (1 paper, 2013). A malignant epithelial neoplasm composed of large, atypical cells. "In H520 squamous lung carcinoma cells and in large cell carcinoma cells (data not shown), the specific silencing of Gli1, Gli2 or Gli3 had a similar effect in cell proliferation and cyclin expression." (PMID 23667589, 2013).
lymphoma (1 paper, 2013). A malignant (clonal) proliferation of B- lymphocytes or T- lymphocytes which involves the lymph nodes, bone marrow and/or extranodal sites. "The activation of GLI1 transcription factor by ALK was reported in a lymphoma cell line and was ascribed to signaling through PI3/Akt." (PMID 24163262, 2013). "It has been reported that ALK induces GLI1 mRNA expression via PI3/Akt in a lymphoma cell line." (PMID 24163262, 2013).
malocclusion (1 paper, 2021). "Gli1+ cells participated in mechanical force-mediated osteogenesis by regulating IP3R-mediated intracellular calcium concentration, suggesting a novel approach for the orthodontic treatment of skeletal malocclusion." (PMID 34434241, 2021).
mantle cell lymphoma (1 paper, 2024). Mantle cell lymphoma is a rare form of malignant non-Hodgkin lymphoma affecting B lymphocytes in the lymph nodes in a region called the ``mantle zone''. "For instance, GANT61 was used to inhibit GLI1 in combination with a Wnt pathway inhibitor, showing enhanced apoptosis and drug sensitivity in mantle cell lymphoma models." (PMID 39596169, 2024).
motor neuron diseases (1 paper, 2020). "The present study provides the evidence for the association of Shh-Gli1 regulation of Crabp1 expression with motor neuron differentiation, and that down-regulation of Crabp1, as well as the Shh-Gli signaling, is associated with motor neuron diseases in humans, such as ALS, SBMA, and SMA." (PMID 32527063, 2020).
Müllerian adenosarcoma (1 paper, 2023). "Meanwhile, MDM2, CDK4, HMGA2, and GLI1 gene amplifications are common molecular events in Müllerian adenosarcoma, often seen in patients with SO." (PMID 37810911, 2023).
odontogenic tumors (1 paper, 2020). "Immunoreactivity for SHH, PTC, SMO, and GLI-1 was detected in both epithelial-derived odontogenic tumors and epithelial-mesenchymal-derived odontogenic tumors with or without dental hard tissue formation." (PMID 33374329, 2020).
olfactory neuroblastoma (1 paper, 2024). An olfactory neuroblastoma arising in the paranasal sinus. "Olfactory neuroblastoma (ONB), another rare tumor of the epithelium in the nasal cavity, also showed activation of the Hedgehog pathway (IHC staining of PTCH1, GLI1, and GLI2), as well as inhibition by Hedgehog pathway inhibitor cyclopamine in vitro on two ONB cell lines." (PMID 38731849, 2024).
Osteochondroma (1 paper, 2021). A common, benign cartiliginous neoplasm arising from the metaphysis of bone. "Western blot results showed that expression of GLI1, MVP, P-p70S6K1, and P-AKT were enhanced in conventional CS as compared to the expression in non-malignant normal cartilage and osteochondroma." (PMID 33637972, 2021).
Osteopenia (1 paper, 2018). Osteopenia is a term to define bone density that is not normal but also not as low as osteoporosis. "Therefore, apart from the depressed osteoblast survival rate caused by increased PTEN, GLI1-meditated activation of Hh in Numb-abated osteoblasts contributed to osteopenia by influencing secretory processes such as RANKL and OPG." (PMID 30455992, 2018).
ovarian serous tumor (1 paper, 2011). A benign, borderline, or malignant epithelial tumor of the ovary characterized by the presence of neoplastic epithelial cells that, in well differentiated tumors, resemble the epithelial cells of the fallopian tube and, in poorly differentiated tumors, show anaplastic features. "Expression data from the micro-dissected stroma in human serous ovarian tumors confirmed the presence of Gli1 transcript and a significant association between elevated Gli1 transcript levels and worsened survival." (PMID 22140510, 2011). "In order to validate that Gli1 mRNA is expressed in the stroma of human serous ovarian tumors, we examined the relative expression of Gli1 in stroma microdissected from a second cohort of 19 human primary ovarian serous tumors." (PMID 22140510, 2011).
papilloma (1 paper, 2019). A benign epithelial neoplasm that projects above the surrounding epithelial surface and consists of villous or arborescent outgrowths of fibrovascular stroma. "This is due to the fact that murine skin expressing normal Gli1 level is significantly more susceptible to chemically-induced papilloma formation than skin with slightly elevated Gli1 levels." (PMID 31867038, 2019). "Together these data indicate that skin of Ptch+/- mice, which express higher Gli1 levels compared to Ptch+/+ skin is less susceptible to chemically-induced papilloma formation than wildtype skin." (PMID 31867038, 2019). "In order to analyze whether the Gli1 expression level of the skin is associated with papilloma formation, Ptch+/+ and Ptch+/- mice that indeed express Gli1 at different level were subjected to the two stage DMBA/TPA carcinogenesis protocol." (PMID 31867038, 2019).
paraganglioma (1 paper, 2025). A benign or malignant neoplasm arising from paraganglia located along the sympathetic or parasympathetic nerves. "However, both WDNETs and paraganglioma also express chromogranin, and the cytokeratin expression in WDNWTs and GATA3 expression in paraganglioma also help differentiate these tumors from GLI1-rearranged enteric tumors." (PMID 39851545, 2025).
Parkinson disease (1 paper, 2010). A progressive degenerative disorder of the central nervous system characterized by loss of dopamine producing neurons in the substantia nigra and the presence of Lewy bodies in the substantia nigra and locus coeruleus. "In summary, this study describes the generation of FP cells from hESC using a single intrinsic factor, GLI1, which may serve as a foundation for deriving various ventral neuronal populations, including mesDA for treating Parkinson's disease." (PMID 20799336, 2010).